LCE6A (late cornified envelope 6A)
Description:
Precursors of the cornified envelope of the stratum corneum.
Synonyms: C1orf44
Tractability: No criterion of Open Targets' tractability assessment is met for any kind of drug.
Gene: Protein-coding gene on chromosome 1 (152,842,856 to 152,843,983, forward strand). Ensembl gene ENSG00000235942.
Pathways (Reactome):
Developmental Biology: Formation of the cornified envelope
Genetic constraint (gnomAD): Loss-of-function variants: 4 observed, 2.02 expected, observed/expected ratio (o/e) 1.98. That is too few expected variants to judge how well the gene tolerates losing a copy. Missense variants: 105 observed, 99.94 expected, observed/expected ratio (o/e) 1.05, 90% interval 0.9 to 1.24. Synonymous variants: 38 observed, 36.31 expected, observed/expected ratio (o/e) 1.05, 90% interval 0.81 to 1.37.
Homologues: Orthologues: chimpanzee LCE6A (96% identical), pig LCE6A (51% identical).
Diseases named in the same sentence as LCE6A in open-access papers:
LCE6A is named in the same sentence as 1 disease in open-access papers, as found by Europe PMC text mining. Sharing a sentence is not in itself a finding about the gene and the disease.
LCE6A shares sentences with these, for which no sentence is quoted: periodontitis (1 paper).